GFAP (glial fibrillary acidic protein)
Diseases named in the same sentence as GFAP in open-access papers (continued):
Sharing a sentence is not in itself a finding about the gene and the disease.
liver fibrosis (12 papers, 2010 to 2025). "HBV-induced liver fibrosis was associated with elevated activation/expansion of human hepatic stellate cells/myofibroblasts as measured by human αSMA- and GFAP-positive cells." (PMID 24651854, 2014). "Among the important structural proteins in hepatic fibrosis, GFAP is highly susceptible to PAD2." (PMID 30071078, 2018). "We investigated to identify dysregulated pathways and gene enrichment based on actin alpha 2 (ACTA2) and glial fibrillar acidic protein (GFAP) interaction network analysis in hepatic fibrosis." (PMID 32494274, 2020). "The GFAP-Cre;Bsgfl/fl and Bsgfl/fl mice were subjected to CCl4 intraperitoneal injection for induction of liver fibrosis." (PMID 29642635, 2018). "GFAP and cit-GFAP immunoreactivity were more intensely stained in the bile duct area of hepatic fibrosis model mice than in sham-operated controls, and these results were correlated with the expression patterns of the western blot analysis." (PMID 30071078, 2018). "In conclusion, we demonstrated for the first time that PAD2 and citrullinated proteins, especially cit-GFAP, are increased in hepatic fibrosis." (PMID 30071078, 2018). "In contrast, recent studies have reported that GFAP-expressing HSCs and myofibroblasts accumulate in and around hepatic fibrosis lesions and that the amount of GFAP increases with the progression of hepatic fibrosis." (PMID 30071078, 2018). "Our study shows that GFAP can be considered as a useful marker for diagnosis of early hepatic fibrosis in CHC patients." (PMID 25225520, 2014). "Since previous reports pointed to the heterogeneity of fibrogenic cells during the development of liver fibrosis, we examined the expression of GFAP and FSP1, markers for hepatic stellate cells and fibroblasts, respectively." (PMID 24349208, 2013). "Previously it was shown that increased GFAP expression marks activated stellate cells in rat liver, and increased levels correlate with hepatic fibrosis in human livers, consistent with the findings herein." (PMID 20814553, 2010). "In addition, our previous study reported that PAD2 and citrullinated proteins, especially citrullinated glial fibrillary acidic protein (GFAP), are increased in hepatic fibrosis." (PMID 36832148, 2023). "pMSCs are able to differentiate into collagenhigh-producing myofibroblasts contributing to kidney or liver fibrosis and express canonical glial markers as glial fibrillary acidic protein (GFAP) and myelin P zero protein (P0), surface markers of astrocytes and Schwann cells respectively." (PMID 36012544, 2022). "Although LX-2 cell line enjoys great popularity among researchers interested in the elucidation of mechanisms underlying stellate cell biology and liver fibrosis, it expresses a-SMA, vimentin, GFAP, and PDGFRb suggesting that cell line retains key features of activated/transdifferentiated HSC." (PMID 32887613, 2020). "Interestingly, GFAP was increased in activated HSCs and GFAP-expressing HSCs, and myofibroblasts accumulated in and around hepatic fibrosis, although vimentin was increased in hepatic fibrosis but not in activated HSCs." (PMID 30071078, 2018). "GFAP-expressing HSCs and myofibroblasts accumulate in and around hepatic fibrosis lesions." (PMID 30071078, 2018). "GFAP was previously found to be expressed in ductular reactions in the livers of mice with choline-deficient ethionine-supplemented diet-induced mouse liver injury, and GFAP is expressed in cholangiocytes in the livers of mice with TAA-induced hepatic fibrosis." (PMID 30071078, 2018). "Finally, we determined the localization of GFAP and cit-GFAP in the livers of the hepatic fibrosis model." (PMID 30071078, 2018). "Our findings implicate that the abnormal accumulation of cit-GFAP may play an important role in the progression of liver fibrosis and that cit-GFAP can be used as a biomarker and a therapeutic target for liver disease." (PMID 30071078, 2018).
liver fibrosis (continued). "Therefore, we focused on citrullination of GFAP in activated HSCs, and we first demonstrate that GFAP generally increases as liver fibrosis progresses, which also increases cit-GFAP." (PMID 30071078, 2018). "Finally, in LE rats, chronic ethanol exposure significantly increased expression of ABST, GFAP, desmin, and collagen, indicating that bile duct epithelium and stellate cells were more activated, and that genes responsible for hepatic fibrosis, that is, desmin and collagen, were up-regulated." (PMID 20814553, 2010). "All these genes are involved in promoting fibrotic changes, especially GFAP, TIMP1, and THBS1, which are expressed by activated hepatic stellate cells, thereby driving liver fibrosis (38, –, 40)." (PMID 40793786, 2025). "However, the involvement of PAD2 and cit-GFAP in hepatic fibrosis remains unclear." (PMID 30071078, 2018). "For the first time, we show the accumulation of cit-GFAP and upregulated PAD2 in bile duct ligation (BDL)-induced hepatic fibrosis." (PMID 30071078, 2018).
mood disorder (12 papers, 2019 to 2025). A cognitive disorder a disturbance in which the person's mood is hypothesized to be the main underlying feature. "Studies report that GFAP levels can mediate expression of glutamate transporters, such that low levels of GFAP are associated with mood disorders, activation of astrocytes influence neurotransmission, and microglial activation triggers astrocyte-mediated modulation of excitatory neurotransmission." (PMID 32038140, 2019). "Overall, this suggests that changes to astrocyte biology in mood disorder could be characterised by either, or both, a reactive, GFAP + phenotype or primarily by a loss of homeostatic function, whereas local injury and inflammatory insult is more consistently associated with reactive astrogliosis." (PMID 40485663, 2025). "Astrocyte biology, typically measured by GFAP expression, was increased in neurodegeneration and acute brain injury models but varied significantly in mood disorder models, depending on the source of stress." (PMID 40485663, 2025). "•Changes to astrocyte biology, shown by GFAP expression, link to brain injury, neurodegeneration, and mood disorders." (PMID 40485663, 2025). "However, given both increased and decreased GFAP expression is considered a feature of mood disorder, and that in general, GFAP expression was a minor outcome of each individual study, it is unlikely to effect the interpretation of our findings." (PMID 40485663, 2025). "Emerging evidence suggests that astrocytes play important roles in influencing brain function and pathology in mood disorders, and Glial Fibrillary Acidic Protein (GFAP) constitutes the major part of the cytoskeleton of astrocytes and is a biomarker for astroglial injury." (PMID 36045388, 2022). "Decreased GFAP in the cerebellum of patients with mood disorders." (PMID 34025481, 2021). "Decreased GFAP protein in the anterior cingulate cortex of patients with mood disorders." (PMID 34025481, 2021). "Thus, we pooled both BPD and MDD patients together in one mood disorder group and compared the day-night differences of GFAP mRNA expression level within this group." (PMID 31798416, 2019). "Whereas GFAP expression tended to be elevated in rodent models of acute brain injury and neurodegeneration, especially AD and PD, GFAP expression was suppressed in five studies of stress-induced mood disorder, and increased in four studies inducing physiological stress." (PMID 40485663, 2025). "These disparities might be due to the difference in age of the patients between our study and Webster’s study as it has been reported that GFAP expression is significantly and positively correlated with age, with more pronounced changes in younger mood disorder patients." (PMID 31798416, 2019). "Moreover, it is not known whether GFAP simply reflects the astrocytic function and/or whether it is directly associated with the symptoms of mood disorders." (PMID 31231189, 2019). "The overall SMD of GFAP expression in models of mood disorder was not significant at SMD -0.05 [−2.64-2.53] with high study heterogeneity (I2 = 87 %) and clear subgroup differences (p < 0.01)." (PMID 40485663, 2025). "Only IOD of GFAP-ir astrocytes was found to be correlated with GFAP mRNA levels in control subjects but not in BPD nor MDD patients, suggesting that regulation of GFAP in astrocytes is impaired or at least abnormal in mood disorders." (PMID 31798416, 2019). "Decreased GFAP expression and reduced numbers of GFAP+ and S100β+ astrocytes are found in the prefrontal cortex, anterior cingulate cortex, and the hippocampus of MDD patients, brain regions that are specifically involved in mood disorders (Torres‐Platas, Nagy, Wakid, Turecki, & Mechawar, 2016)." (PMID 31038797, 2019). "We showed that there is a clear day-night GFAP fluctuation in the DLPFC in control subjects, however, in the mood disorder patients this diurnal difference was absent." (PMID 31798416, 2019).
mood disorder (continued). "Finally, a remarkable diurnal pattern of GFAP mRNA expression appeared to be present in the DLPFC of healthy controls, but not in mood disorder patients." (PMID 31798416, 2019). "In addition, a remarkable diurnal pattern of the GFAP mRNA expression appeared to be present in the DLPFC of controls, but not in mood disorder patients." (PMID 31798416, 2019).
type 1 diabetes (12 papers, 2013 to 2025). "The literature on mouse models shows increased GFAP expression in models of type 1 diabetes, chemotherapy, and inflammation." (PMID 34440226, 2021). "GFAP can delay the development of type 1 diabetes by regulating T cell differentiation." (PMID 33509222, 2021). "Müller cells that do not express GFAP under physiological conditions are known to express GFAP in pathological situations, including experimental type 1 diabetes." (PMID 25004165, 2014). "Furthermore, although GFAP-specific T cells isolated from MS patients have not been studied, GFAP-specific CD8 T cells have been isolated from patients with type 1 diabetes, indicating that human T cells with this reactivity pattern populate the peripheral T cell repertoire." (PMID 26300731, 2015).
gliosarcoma (11 papers, 2017 to 2025). A rare histological variant of glioblastoma (WHO grade IV) characterized by a biphasic tissue pattern with alternating areas displaying glial and mesenchymal differentiation (WHO). "The gliomatous component of gliosarcoma marked by GFAP (glial fibrillary associated protein) staining displayed foci of necrosis surrounded by dense tumor cells; this palisading necrosis is a characteristic feature of GBM." (PMID 30818875, 2019). "Experimental models have also demonstrated that GFAP (Glial Fibrillary Acidic Protein), typically associated with astrocytic structure and function, is upregulated in gliosarcoma, reflecting astrocytic activation and the establishment of a supportive environment for neuronal repair." (PMID 40806177, 2025). "The majority of the viable tumor from the first resection exhibited the biphasic morphological and staining pattern of gliosarcoma, with mutually exclusive GFAP-positive glial and reticulin-positive sarcomatous areas." (PMID 35932030, 2022). "The majority of the viable tumor from the first resection exhibited the biphasic morphological and staining pattern of gliosarcoma, with mutually exclusive GFAP-positive glial and reticulin-positive sarcomatous areas (Frontotemporal mass)." (PMID 32014051, 2020). "All cases were diagnosed as gliosarcoma, the glial component of which, exhibited confirmatory GFAP immunohistochemical positivity." (PMID 31073965, 2019). "Gliosarcomas were excluded according to established histologic and immunohistological criteria (GFAP, vimentin and reticulin staining)." (PMID 28881571, 2017). "In addition to podoplanin, studies involving gliosarcoma models have demonstrated the upregulation of other proteins such as glial fibrillary acidic protein (GFAP) and von Willebrand factor (vWF)." (PMID 40806177, 2025). "GFAP was regarded to be only expressed in gliosarcomas and hemangioblastomas, but some studies have reported that GFAP may be sporadically positive in a few CM patients." (PMID 36438949, 2022). "Final pathology from the resected specimen was WHO IV gliosarcoma with biphasic tissue architecture, comprised of prominent GFAP-positive glial regions admixed with GFAP-negative spindled areas containing reticulin fibers." (PMID 33580181, 2021).
anaplastic astrocytoma (10 papers, 2010 to 2024). "GBM and anaplastic astrocytoma occur from astroglial cells, and GFAP is the most widely used marker of astroglial cells." (PMID 27494894, 2016). "In the 2 grade III anaplastic astrocytomas, 80–90% of the tumor cells were glial fibrillary acidic protein (GFAP) positive and 30–40% of the tumor cells showed low level Endo180 expression." (PMID 20339555, 2010).
Hypoglycemia (10 papers, 2019 to 2025). A decreased concentration of glucose in the blood. "It has been reported that hypoglycemia-associated brain damage developed and GFAP release increased in rats experimentally induced with hypoglycemia." (PMID 38026658, 2023). "High GFAP concentrations have been associated with hypoglycemia-induced glial damage, astrocyte activation and neuroprotective role." (PMID 38026658, 2023). "On a semiquantitative scale, the hypoglycemic rats showed a significant increase in GFAP-labeled astrocytes at both 7 and 90 days post-hypoglycemia compared to control rats." (PMID 39004753, 2024). "GFAP immunostaining unveiled highly reactive astrocytes in rats subjected to recurrent severe hypoglycemia, displaying typical features such as dark enlarged cell bodies and thick processes distributed across the brain cortex and hippocampus." (PMID 39004753, 2024). "Our results showed that significant changes in S100B, NSE, GFAP, UCHL-1, ACT concentrations, and CK-BB enzyme activity occurred in calves with diarrhea related to hypoglycemia, and hypoglycemia was associated with high mortality." (PMID 38026658, 2023). "A positive correlation between Aqp-4 and GFAP protein levels are consistent with prior reports of increased Aqp-4 corresponding with increased gliosis in a model of hypoglycemia." (PMID 31708792, 2019). "This would allow determining whether the ability of IF to reduce GFAP immunoreactivity responds to direct modulation of epileptogenic mechanisms or metabolic changes in glial cells induced by hypoglycemia." (PMID 40232534, 2025). "This evidence is reminiscent of the reduction in GFAP without any hypothalamic cell loss that has been correlated to the initial stages of hypoglycemia." (PMID 36732488, 2023). "Based on these findings, it is tempting to speculate that the genetic inactivation on Glut2 in GFAP-expressing tanycytes generates a hyperactivation of VMN SF1 neurons (in hypoglycemia condition), leading to suppression of feeding after fasting." (PMID 36271117, 2022). "We performed CD11b and GFAP staining, which is an inflammatory marker, to confirm the neuroprotective effects of DCA on inflammation induced by microglia and astrocyte activation after hypoglycemia." (PMID 31052436, 2019). "However, it is expected that in case of prolonged exposure of brain cells to such pathological conditions (e.g. hypoxia due to pulmonary embolism or severe hypoglycemia) GFAP levels increase over time, along with subsequent (but not rapid) glial necrosis." (PMID 38581002, 2024). "None of S100B, NSE, GFAP, UCHL-1, ACT, AM, and CK-BB were found to be significant (p > 0.05) in predicting mortality in calves with hypoglycemia." (PMID 38026658, 2023).
peripheral nerve injury (10 papers, 2011 to 2024). Injury to a peripheral nerve. "The use of guanfacine was also associated with a decrease in GFAP‐positive cells in the prefrontal lobe and cingulate gyrus, just as activation of microglial cells in the spinal cord after peripheral nerve injury may make pain persist." (PMID 37721421, 2024). "With regard to astrocytes, GFAP is commonly used as an activation marker due to its robust upregulation observed across several pathological conditions, including peripheral nerve injuries." (PMID 37082205, 2023). "Our work has investigated the specific role of the GFAP in the maladaptive synaptic process following peripheral nerve injury." (PMID 35406788, 2022). "Comparing the sources of equine MSCs subjected to the induction medium, we observed that the gene expression of GFAP and S100β was significantly higher in equine AT-MSCs, which is the best candidate for cell-based therapy in the context of peripheral nerve injuries." (PMID 37071193, 2023). "In addition to microglia, peripheral nerve injuries also induce spinal astrocyte activation with increased glial fibrillary acidic protein (GFAP) expression." (PMID 34183051, 2021). "For instance, transgenic inhibition of NF-κB in glial fibrillary acidic protein (GFAP) expressing glial cells attenuated pain and neuronal inflammation after peripheral nerve injury." (PMID 32454918, 2020). "Our data suggest that dorsal horn microglia, but not astrocytes, undergo substantial morphologic/phenotypic changes by middle age, and that GFAP protein expression in astrocytes does not necessarily accompany the establishment of pain following peripheral nerve injury." (PMID 26241743, 2015).
proteinopathies (10 papers, 2019 to 2025). "To gain insights into the distribution of inflammatory signals and the potential association with areas of marked proteinopathy, we evaluated Iba1 and GFAP immunoreactivity by immunofluorescence." (PMID 33919140, 2021). "In addition to the emergence of compound proteinopathies in wide brain regions, we performed IHC with antibodies specific for Iba1, GFAP and TNFα to assess the extent of gliosis and neuroinflammation, which are key features in neurodegenerative diseases." (PMID 40307569, 2025). "Finally, GFAP showed comparable values among the FTD clinical syndromes and proteinopathies." (PMID 31892365, 2019).
ulcerative colitis (10 papers, 2011 to 2024). An inflammatory bowel disease involving the mucosal surface of the large intestine and rectum. "In an RNA sequencing profile comparing colonic mesenchyme between healthy and ulcerative colitis mice, glial cells were typically clustered by the expression of their markers S100B and GFAP, and possible additional markers include Hapln1 and POSTN." (PMID 37551711, 2024). "For example, high GFAP and S100β expression is a feature of mucosal inflammation in patients with ulcerative colitis (UC) or Crohn’s disease (CD)." (PMID 37779161, 2023). "GFAP expression has been found to be altered in the mucosa of patients with ulcerative colitis (UC) and Crohn’s disease." (PMID 36322182, 2023). "In ulcerative colitis (UC) patient biopsies, mucosal GFAP expression levels are significantly elevated in inflamed region whereas in Crohn’s disease (CD) patients GFAP expression levels are lower and even significantly reduced in non-inflamed mucosal biopsies compared to healthy controls." (PMID 26964064, 2016). "Ulcerative colitis patients had significantly lower serum S100B levels, while GFAP was of no diagnostic value in UC patients." (PMID 24790767, 2014). "The expression of GFAP and GDNF in the mucosal plexus is highly increased in the inflamed colon of patients with ulcerative colitis (UC) and infectious colitis." (PMID 21235736, 2011). "However, lower glial fibrillary acidic protein (GFAP) and GDNF levels in CD compared with ulcerative colitis and infectious colitis indicate a weaker enteric glial cell network in this condition." (PMID 37551711, 2024).